CEACAM1 (CEA cell adhesion molecule 1)
Diseases named in the same sentence as CEACAM1 in open-access papers (continued):
Sharing a sentence is not in itself a finding about the gene and the disease.
candida infection (2 papers, 2019 to 2022). "Based on previous reports and on the present study, we considered thatC. albicansbinds to CEACAM1 in oral keratinocytes during candida infection of oral epithelium, and that β-glucan exposed on surface ofC. albicanscan activate CEACAM1 expression." (PMID 36350873, 2022). "In this study, we therefore analyzed the influence of human CEACAM1 expression on the host immune reaction to C. albicans in a C. albicans colonization and dissemination mouse model mimicking a gastrointestinal tract-derived systemic candidiasis and in a systemic model of candidiasis." (PMID 31849868, 2019). "Taken together, we found that the presence of human CEACAM1 in transgenic mice was not sufficient to alter the host immune response to C. albicans in two different models of systemic candidiasis." (PMID 31849868, 2019). "In conclusion, in contrast to bacterial pathogens interacting with CEACAM1 on different mucosal surfaces, the human CEACAM1-transgenic mice did not reveal a role of human CEACAM1 in the in vivo candidiasis models used here." (PMID 31849868, 2019).
chronic obstructive pulmonary disease (2 papers, 2014 to 2019). A chronic and progressive lung disorder characterized by the loss of elasticity of the bronchial tree and the air sacs, destruction of the air sacs wall, thickening of the bronchial wall, and mucous accumulation in the bronchial tree. "Furthermore, it has been reported that UspA1 protein of M. catarrhalis induces CEACAM1-dependent apoptosis in alveolar epithelial cells and that this might contribute to the pathogenesis of chronic obstructive pulmonary disease (COPD)." (PMID 24599281, 2014). "It has been reported that the UspA1 protein of M. catarrhalis induces CEACAM1-dependent apoptosis in alveolar epithelial cells and that this might contribute to the pathogenesis of chronic obstructive pulmonary disease (COPD)." (PMID 24599281, 2014).
Cirrhosis (2 papers, 2021 to 2023). A chronic disorder of the liver in which liver tissue becomes scarred and is partially replaced by regenerative nodules and fibrotic tissue resulting in loss of liver function. "CEACAM1 interacts with TNFα, playing a pathogenic role in cirrhosis-related hyperpermeability." (PMID 36741860, 2023). "Interrupting interactions between CEACAM1 and TNFα might prove effective in preventing cirrhosis-related hyperpermeability." (PMID 36741860, 2023).
colorectal adenoma (2 papers, 2023 to 2024). An adenoma that arises from the colon or rectum. "CEACAM-1 downregulation is reported in > 85% of early colorectal adenomas and carcinomas; vice versa, its overexpression is detected in advanced stages of malignancies." (PMID 39285481, 2024). "As an example, CEACAM1 were reported to be aberrant upregulated in colorectal adenoma and adenocarcinoma, and the protein intensity was correlated with the TNM staging." (PMID 36759883, 2023).
Crohn disease (2 papers, 2016 to 2025). A gastrointestinal disorder characterized by chronic inflammation involving all layers of the intestinal wall, noncaseating granulomas affecting the intestinal wall and regional lymph nodes, and transmural fibrosis. "A different report shows an opposite correlation between SOX9 and CEACAM1 in Crohn's disease." (PMID 26885752, 2016).
cutaneous melanoma (2 papers, 2016 to 2019). A primary melanoma arising from atypical melanocytes in the skin. "It was reported that serum carcinoembryonic antigen cell adhesion molecule-1 (CEACAM-1) correlated with disease progression and survival in malignant cutaneous melanoma patients." (PMID 30867659, 2019). "CEACAM1 was identified in 45% of the primary uveal melanomas and in 81% of liver metastases, similar to CEACAM1 expression in cutaneous melanoma and its corresponding metastases." (PMID 27642217, 2016). "The selected candidate proteins in this study have been recently assessed in UM (i.e. OPN, MIA, CEACAM-1, MIC-1, and HSP27) and/or cutaneous melanoma as well as other cancers (i.e. SPON1 and POSTN) by either ELISA or immunohistochemistry or other techniques." (PMID 30867659, 2019).
dyslipidemia (2 papers, 2017 to 2023). "CEACAM1 is downregulated in individuals with the metabolic syndrome and its downregulation enhances a vicious circle leading to worsening of NAFLD." (PMID 37511031, 2023).
dysplastic nevi (2 papers, 2016 to 2018). "CEACAM1 expression was significantly higher in SSM compared to benign nevi, and the authors noticed a progressive increase from benign nevi, dysplastic nevi, and thin SSM to thick SSM." (PMID 27642217, 2016).
gastric adenocarcinoma (2 papers, 2021). "In healthy tissue, no CEACAM1 expression was found but it was upregulated in tissue samples presenting gastric inflammation induced by H. pylori as well as in gastric adenocarcinomas, where CEACAM1 may be involved in tumor angiogenesis." (PMID 34442827, 2021). "A positively correlation was also noted between mRNA expression of CEACAM-1 or MHC class II and that of PD-L1 in TCGA stomach adenocarcinoma tissue dataset (r = 0.22 and p < 0.0001, r = 0.42 and p < 0.0001 respectively)." (PMID 33611641, 2021). "This was in concordance with the observation in TCGA stomach adenocarcinoma tissue dataset analysis, showing a significant correlation between CD8 T effector gene signature and mRNA expression levels of PD-L1, CEACAM-1, and MHC class II, but not LSECtin." (PMID 33611641, 2021).
graft versus host disease (2 papers, 2025). An immune system disorder that occurs after allogeneic hematopoietic stem cell transplant and is a reaction of donor immune cells against host tissues. "A humanized mouse model of xenogeneic graft-versus-host disease demonstrates that BLIMP-1 normally promotes, while CEACAM1 restrains, Treg suppressive activity." (PMID 40773294, 2025).
HCMV infection (2 papers, 2014 to 2019). "CEACAM-1 (immunoglobulin family) was upregulated 20-fold by HCMV infection and may have roles in T cell regulation." (PMID 24906157, 2014). "Recently, NK cell adaptation and HCMV infection have been shown to enhance NK cell expression of PD-1, TIM-3 and CEACAM-1 (CD66a), inhibitory molecules whose signaling slows NK cell proliferation and diminish NK cell pro-inflammatory activities." (PMID 31627371, 2019).
head and neck squamous cell carcinoma (2 papers, 2021 to 2025). A squamous cell carcinoma that arises from any of the following anatomic sites: lip and oral cavity, nasal cavity, paranasal sinuses, pharynx, larynx, and salivary glands. "Blocking CEACAM1 using targeted antibodies or small molecules may restore the body’s anti-tumor immunity and represents a promising new immunotherapy approach for head and neck squamous cell carcinoma (HNSCC)." (PMID 40519270, 2025).
ischemic stroke (2 papers, 2022 to 2024). A stroke disorder caused by obstruction of blood flow to the brain, due to thrombotic (local blood clot formation) or embolic (due to a blood clot or other material traveling from another site) event. "This study aims to analyze the level of carcinoembryonic antigen‐related cell adhesion molecule 1 (CEACAM1) in neutrophils at different stages of ischemic stroke (IS), together with the roles of CEACAM1 on neutrophils." (PMID 35657334, 2022). "We aimed to analyze the level of carcinoembryonic antigen‐related cell adhesion molecule 1 (CEACAM1) in neutrophils of ischemic stroke (IS) patients at different stages, together with its roles in neutrophils." (PMID 35657334, 2022).
laryngeal squamous cell carcinoma (2 papers, 2021 to 2025). A squamous cell carcinoma that arises from the larynx. "Similar to our results, the function of CEACAM1 has been confirmed in ovarian tumors, oral tumors and laryngeal squamous cell carcinoma (LSCC)." (PMID 34368221, 2021).
Listeria monocytogenes infection (2 papers, 2019 to 2021). "Upon Listeria monocytogenes infection in mice, IL-6 production is also influenced by carcinoembryonic antigen-related cell adhesion molecule-1 (CEACAM1) via the G-CSFR-STAT3 pathway." (PMID 34414191, 2021). "In agreement with this role for CEACAM1, we have previously shown that CEACAM1 regulates granulopoiesis and the systemic response to Listeria monocytogenes infection via the G-CSFR-STAT3 pathway, and the IL-1β response to LPS in neutrophils by a TLR4-Syk pathway." (PMID 30674283, 2019).
liver cancer (2 papers, 2021 to 2024). An epithelial or non-epithelial malignant neoplasm that arises from the liver. "Recently, it has been confirmed that decreasing CEACAM1 expression in liver cancer cells (Mahlavu and SK-Hep-1) may inhibit invasion and migration of tumor cells." (PMID 39513107, 2024).
mastocytosis (2 papers, 2017 to 2018). A clonal myeloproliferative neoplasm characterized by the proliferation and accumulation of neoplastic mast cells in one or multiple organs or organ systems. "CEACAM1 knockdown upregulated cell growth of HMC1.2 cells harboring KIT mutations detected in clinical mastocytosis, whereas downregulated the growth of TT cells harboring RET mutations detected in clinical MTCs." (PMID 28332308, 2017). "Studies assessing CEACAM1 isoform expression in human neoplastic mast cells (mastocytosis) and medullary thyroid carcinoma cell (MTC) lines suggest that CEACAM1-L enhances cell growth in association with preferential interactions and activation of SFKs." (PMID 30406153, 2018). "Here, we report that CEACAM1 was uniquely expressed at high levels in both human neoplastic mast cells (mastocytosis) and medullary thyroid carcinoma cell (MTC) lines, when compared with their expression in nonneoplastic mast cells or nonneoplastic C cells." (PMID 28332308, 2017). "We therefore examined the expression and function of CEACAM1 in neoplastic mast cells (mastocytosis) and MTCs of human origin." (PMID 28332308, 2017). "CEACAM1 expression on mast cells in the skin biopsies of mastocytosis patients was evaluated by immunohistochemical staining." (PMID 28332308, 2017). "As is the case for mastocytosis, CEACAM1 protein expression was observed in most MTCs and C cells with RET mutations, but not in C cells with normal RET." (PMID 28332308, 2017).
meningococcal infection (2 papers, 2011 to 2013). Infections with bacteria of the species neisseria meningitidis. "In contrast to the IgA-dominated mucosal response to meningococcal infection of the CEACAM1-humanized mice, immunity conferred by the vaccine correlated with Nme-specific IgG without any IgA response being apparent in either mouse genotype." (PMID 23935487, 2013). "Perhaps more surprisingly, the innate inflammatory response to meningococcal infection relied on bacterial Opa expression and human CEACAM1 expression in the tissues." (PMID 23935487, 2013). "Mice expressing other human CEACAMs were not colonized, highlighting the central importance of CEACAM1 for meningococcal infection." (PMID 23935487, 2013). "Unstimulated primary endothelial cells do not express CEACAMs, but a strong upregulation of CEACAM1 is observed upon stimulation with pro-inflammatory cytokines such as TNFα, which is induced during meningococcal infection." (PMID 21298042, 2011).
multiple myeloma (2 papers, 2021 to 2023). "MSTRG.155519 played a carcinogenic role in myeloma by targeting CEACAM1; MSTRG.13132 was related to FAM46C." (PMID 34108986, 2021).
oral cancer (2 papers, 2023 to 2024). "The relatively consistent findings were confirmed in oral cancer, where CEACAM1 was associated with these signaling pathways, and low expression of CEACAM1 in oral cancer led to worse prognosis." (PMID 39513107, 2024). "The expression level of CEACAM1 in oral cancer samples was lower than that in normal samples, and after CEACAM1 knockdown, the expression level was lower than that in oral cancer samples and overexpression samples." (PMID 37589542, 2023). "The main result of this study is that CEACAM1 is underexpressed in oral cancer, and the lower CEACAM1, the worse the prognosis." (PMID 37589542, 2023). "Western blotting (WB) showed that CEACAM1 in oral cancer samples was lower than that in normal samples, after CEACAM1 knockdown, it was lower than that in oral cancer samples." (PMID 37589542, 2023). "CEACAM1 may serve as a molecular target for precision treatment of oral cancer and provide a definite directional basis for the mechanistic study of oral cancer." (PMID 37589542, 2023). "It is therefore speculated that CEACAM1 may play an important role in processes such as cell adhesion and migration in oral cancer." (PMID 37589542, 2023). "In conclusion, CEACAM1 is underexpressed in oral cancer and may play a significant role in the development of oral cancer through pathways such as cell regulation." (PMID 37589542, 2023). "And the core gene (CEACAM1) was lowly expressed in oral cancer samples and highly expressed in normal samples, which may have a reverse regulatory effect on oral cancer." (PMID 37589542, 2023). "Public datasets were utilized to validate role of CEACAM1 in oral cancer." (PMID 37589542, 2023). "However, the relationship between CEACAM1 and oral cancer is unclear." (PMID 37589542, 2023). "However, the relationship between CEACAM1 and oral cancer is unclear at present." (PMID 37589542, 2023).
osteosarcoma (2 papers, 2016 to 2023). A usually aggressive malignant bone-forming mesenchymal neoplasm, predominantly affecting adolescents and young adults. "In the present study, we evaluated serum CEACAM1 level in osteosarcoma patients to explore its diagnostic and prognostic value for this particular malignancy." (PMID 27074014, 2016). "The present study suggested that elevated serum CEACAM1 level might be a novel diagnostic and prognostic biomarker for osteosarcoma patients." (PMID 27074014, 2016). "The results revealed that serum CEACAM1 level was significantly higher in osteosarcoma patients compared to benign bone tumors and healthy controls (455.2 ± 179.9 vs 287.4 ± 103.2, 260.8 ± 109.7 pg/ml, respectively)." (PMID 27074014, 2016). "Osteosarcoma patients with larger tumors, later-tumor stages, low tumor grades, and distant metastases had much higher CEACAM1 compared to those with smaller tumors, earlier tumor stages, high tumor grades and non-distant metastases (P < 0.05 for all)." (PMID 27074014, 2016). "Osteosarcoma patients with higher CEACAM1 had relatively lower survival compared to those with low CEACAM1 (P < 0.01), and multivariate analyses for overall survival revealed that high serum CEACAM1 level was an independent prognostic factor for osteosarcoma (HR = 1.56, 95%CI 1.23–3.28)." (PMID 27074014, 2016). "Most gene targets commonly investigated in ACT of other solid tumors except osteosarcoma, such as CEACAM1, PSCA, MSLN, IL13RA2, and GPC3, showed low or nonspecific expression in osteosarcoma compared with adjacent normal tissues." (PMID 37457661, 2023).
ovarian tumors (2 papers, 2018 to 2021). "Further analysis showed a predominance of 4S and 4L isoforms and mostly membraneous CEACAM1 localization in ovarian tumours." (PMID 30050594, 2018).
pericarditis (2 papers, 2016 to 2018). An inflammatory process affecting the pericardium. "Clinically, the evidence point on a potential diagnostic relevance of serum CEACAM1 in pericarditis patients, which should be further explored in larger prospective clinical trials." (PMID 26909604, 2016). "Further mechanistic studies are mandated, including a biochemical analysis of the serum CEACAM1 in the pericarditis patients." (PMID 26909604, 2016). "ROC curves showed an extremely high accuracy of serum CEACAM1 in pericarditis patients, with AUC values of 0.995 and 0.943 for AP and RP patients, respectively." (PMID 26909604, 2016). "Here we report for the first time on CEACAM1 as a potentially novel biomarker for pericarditis, as well as on MICA as an innovative prognostic marker in these patients." (PMID 26909604, 2016). "CEACAM1 is detectable in serum, and it has been used as a marker for pericarditis." (PMID 29467960, 2018). "As some of these conditions may play a role in pericarditis, upregulation of CEACAM1, MICA or MICB could be anticipated in situ." (PMID 26909604, 2016). "Here we investigate the involvement of serum CEACAM1, MICA and MICB, proteins that can be induced in damaged or inflamed tissues, in pericarditis patients." (PMID 26909604, 2016). "Collectively, these prompted the investigation of serum CEACAM1, MICA and MICB in pericarditis patients." (PMID 26909604, 2016).
tongue squamous cell carcinoma (2 papers, 2014 to 2025). A squamous cell carcinoma that arises from the tongue. "The present study aimed to explore the clinical significance of neutrophils infiltration and carcinoembryonic antigen related cell adhesion molecule 1 (CEACAM1) expression in the tongue squamous cell carcinoma (TSCC), and to probe the possible relationship between them." (PMID 24587171, 2014).
type 1 diabetes (2 papers, 2021 to 2025). "We hypothesise that autoimmune inflammation associated with type 1 diabetes leads to increased expression of the hepatic CEACAM1, increasing insulin clearance in rapid disease progressors." (PMID 39560746, 2025).
uveal melanoma (2 papers, 2016 to 2022). A melanoma derived from melanocytes of the uveal tract. "In their review, carcinoembryonic antigen (CEACAM-1) showed an increased level in uveal melanoma but was rarely used in uveal melanoma as it may be confused with other malignancies." (PMID 36475154, 2022).
acute myeloid leukemia (1 paper, 2021). Acute myeloid leukemia (AML) is a group of neoplasms arising from precursor cells committed to the myeloid cell-line differentiation. "The decreased expression of CEACAM1 and EPHA2 was found to be associated with several cancers, but ITGB5 reduction in expression was associated with acute myeloid leukemia (LAML) only." (PMID 34908921, 2021).
adrenocortical carcinoma (1 paper, 2021). "Furthermore, data from bioinformatical analyses have implicated that ANAX1, CYR61, and VIM are mainly associated with the development of PAAD and GBM, while CEACAM1 and EPHA2 are associated with adrenocortical carcinoma." (PMID 34908921, 2021).
Arthritis (1 paper, 2024). Inflammation of a joint. "In CEACAM1, YBX3 and SLC6A8, all three genes were found to be overexpressed in patients with arthritis associated with fever." (PMID 38243323, 2024).
asthma (1 paper, 2025). "For instance, PAD4 expression positively regulates NETs in severe asthma, and CEACAM1 influences NET formation by regulating the S1P-S1PR2/S1PR3 axis." (PMID 40452820, 2025).
B cell deficiency (1 paper, 2015). A broad classification of disorders where circulating numbers of B lymphocytes are decreased or ineffective. "Therefore, we would suggest that lack of CEACAM1 could be another factor explaining B-cell deficiency in humans." (PMID 25692415, 2015).
benign bone tumors (1 paper, 2016). "Serum CEACAM1 may be a diagnostic biomarker to distinguish OS from benign bone tumors and controls, and can distinguish advanced from early OS stages." (PMID 27074014, 2016). "Serum CEACAM1 level was elevated in OS patients compared to those with benign bone tumors and controls (455.2 ± 179.9 vs 287.4 ± 103.2, 260.8 ± 109.7 pg/ml, respectively)." (PMID 27074014, 2016). "Also, ROC data confirmed low sensitivity for CEACAM1 to differentiate OS patients from those with benign bone tumors and controls." (PMID 27074014, 2016). "Patients with benign bone tumors had slightly higher serum CEACAM1 level than healthy controls, but this was not significant (P = 0.17)." (PMID 27074014, 2016).
benign epithelial tumors (1 paper, 2021). "Therefore, substitutive tests in normal epithelium and benign epithelial tumors are required to confirm the importance of TIM-3 and CEACAM1 in tumorigenesis of HNSCC." (PMID 34368221, 2021). "Secondly, the expression of TIM-3 and CEACAM1 in normal head and neck (oral/oropharyngeal/nasopharyngeal/labial/lingual) epithelium and primary benign epithelial tumors were not determined in our study." (PMID 34368221, 2021).